TLR3 (toll like receptor 3)
Diseases named in the same sentence as TLR3 in open-access papers (continued):
Sharing a sentence is not in itself a finding about the gene and the disease.
hepatitis C virus infection (5 papers, 2010 to 2023). A viral infection caused by the hepatitis C virus. "In viral hepatitis C at least two of them, RIG-1 and TLR3 sense HCV, induce protective interferon production and create proinflammatory status." (PMID 32944845, 2020). "For example, the response against hepatitis C virus infection is mediated by the TLR2 and TLR3 signaling, while West Nile Virus (WNV) can be recognized by TLR-3, eliciting an antiviral response shaping innate as well as adaptive immunity in in vivo experiments." (PMID 21200427, 2010).
lymph node metastasis (5 papers, 2022 to 2025). "Notably, an obvious increase of nuclear TLR3 was observed in lymph node metastasis relative to primary lesions." (PMID 40675966, 2025). "Regarding TLR3, negative immunostaining in CRC tissue was recently associated with lymph node metastasis and TLR3 has been indicated as an independent risk factor for recurrence of CRC." (PMID 36433652, 2022).
mesothelioma (5 papers, 2020 to 2023). A usually malignant and aggressive neoplasm of the mesothelium which is often associated with exposure to asbestos. "In most preclinical and epidemiological studies, high TLR3 expression and/or activation is associated with a favorable prognosis, including in bladder cancer, mesothelioma, NSCLC, HCC, and breast cancer carcinoma." (PMID 37275475, 2023). "In addition, TLR3 acts directly as a death receptor in cancer cells of various origins including breast, melanoma, mesothelioma, head and neck, prostate, renal carcinoma, colon, oral, and lung cancer cells." (PMID 37275475, 2023). "Moreover, the protective effect of CpG stimulation, and to a lesser extent of TLR3 and TLR7/8, and the role of IL-12 in this protection were confirmed in a model of early mesothelioma AB1 cell growth." (PMID 36714124, 2022).
nasal polyp (5 papers, 2015 to 2022). "So far, a similar level of induction of IL-6, IL-8, and IL-33 in the epithelia of healthy controls and nasal polyposis patients in responses to different bacterial TLR agonists was shown with the viral analogue poly(I:C) (TLR-3 agonist)." (PMID 27050744, 2016). "The TLR3 agonist and viral analogue poly(I:C) induced TSLP mRNA 13.0 ± 3.1 fold (p < 0.05) and protein expression by 12.1 ± 2.3-fold (p < 0.05) higher in epithelium isolated from nasal polyposis patients than in epithelium form healthy controls." (PMID 27050744, 2016). "Polycytidylic acid (poly (IC)) is the ligand for TLR3, and exposure to poly (IC) selectively induces IL-10, but not IL-5, IL-13, IFN-γ or IL-17A, production by nasal polyp cells." (PMID 36003393, 2022).
Parkinson disease (5 papers, 2015 to 2026). A progressive degenerative disorder of the central nervous system characterized by loss of dopamine producing neurons in the substantia nigra and the presence of Lewy bodies in the substantia nigra and locus coeruleus. "Toll-like receptor 3 (TLR3) is classically known for mediating inflammatory pathways in Parkinson's disease (PD)." (PMID 41717640, 2026). "Moreover, the rs3775290 of TLR3 might be a protective factor for sporadic parkinson’s disease in Han Chinese population." (PMID 36386838, 2022). "In the brain, α-synucleinopathies such as Parkinson’s disease (PD) and Lewy body dementia (LBD) show immune cytokine network activation and increased toll like receptor 3 (TLR3) levels for viral double-stranded RNA (dsRNA)." (PMID 37704739, 2023).
pneumococcal infection (5 papers, 2020 to 2024). Infections with bacteria of the species streptococcus pneumoniae. "Previously, we described that pneumococcal infection is more severe after the TLR3 activation or RVS infection." (PMID 39766307, 2024). "When the NV1505 and PG1505 treatments were administered 4 days before stimulation with poly(I:C), they were equally efficient in improving the response to secondary pneumococcal infection compared to administration 2 days before TLR3 activation." (PMID 36363777, 2022). "The simultaneous absence of TLR3/7/9 was associated with a significant reduction in early influx into the lung of neutrophils, which are primarily responsible for clearing pneumococcal infection." (PMID 32209688, 2020). "To identify relevant TLRs, we tested mice lacking TLR3, TLR7, TLR9, or TLR13, as well as TLR7/9−/− double knockout (KO) mice, for their ability to control pneumococcal infection." (PMID 32209688, 2020).
Acute hepatitis (4 papers, 2013 to 2026). Acute hepatic injury resulting from inflammation typically accompanied by increased serum alanine transaminase activity. "Here, we add TLR3 mediated expression of IL-33 in liver sinusoidal endothelial cells, vascular endothelial cells and hepatocytes in acute hepatitis in mice in a pathophysiological context." (PMID 24058536, 2013). "To investigate whether LIGHT plays a role in the pathogenesis of TLR3-triggered acute hepatitis, we blocked the LIGHT signaling pathway with recombinant HVEM-Fc fusion protein, which blocks interaction of LIGHT with its receptor HVEM." (PMID 36654880, 2023). "Therefore, this study evaluated whether this immunomodulatory bacterium protects against Toll-like receptor 3 (TLR3)-mediated acute hepatitis induced by poly(I:C), and whether this effect depends on mucosal adhesion." (PMID 41897754, 2026).
age-related macular degeneration (4 papers, 2011 to 2016). Age-related loss of vision in the central portion of the retina (macula), secondary to retinal degeneration. "Single nucleotide polymorphisms in TLR3 leading to inappropriate TLR3 expression or defective signaling are linked to increased severity of human herpesvirus and influenza virus infection and age-related macular degeneration." (PMID 22039520, 2011). "Association of a polymorphism rs3775291 in the toll-like receptor 3 (TLR3) gene with age-related macular degeneration (AMD) had been investigated intensively, with variable results across studies." (PMID 26796995, 2016). "A recent study showed that TLR polymorphisms have been associated with age-related macular degeneration (AMD) and investigation on the utility of small interfering RNA treatment for AMD identified that small interfering RNA was signaling through TLR3." (PMID 23401658, 2013).
AIDS (4 papers, 2012 to 2021). A syndrome resulting from the acquired deficiency of cellular immunity caused by the human immunodeficiency virus (HIV). "Although they have demonstrated some benefit as immunotherapy agents against cancer, AIDS and CFS/ME, TLR3 agonists also cause adverse effects in some individuals and have not yet been authorised for use in vaccines." (PMID 33499143, 2021). "The expression of TLR3, 7, and 9 in Muller glia and their activation with respective ligands implicates the role of Muller glia in antiviral innate defense, potentially in viral retinitis in AIDS patients." (PMID 22253793, 2012).
aspergillosis (4 papers, 2012 to 2024). Aspergillosis is an infection, growth, or allergic response caused by the Aspergillus fungus. "In humans, the single nucleotide polymorphism (SNP) of TLR3 provides more invasive aspergillosis." (PMID 33194839, 2020). "Because the activation of TLR3-dependent pathways in both epithelial cells and dendritic cells (DCs) has been shown to confer resistance to aspergillosis, TLR3 was also suggested to participate in the recognition of fungal nucleic acids." (PMID 38651925, 2024). "In aspergillosis, the TLR3 role in DCs is of great relevance, being critical both for its maturation and the production of type I IFN." (PMID 33194839, 2020). "In mice, the susceptibility to aspergillosis is increased in conditions of TLR3 absence, leading to an increase in the inflammatory process in murine aspergillosis, accompanied by a decrease in the production of IFN-γ, IL-10." (PMID 33194839, 2020). "In pulmonary aspergillosis, TRIF−/− mice as well as TLR3−/− mice are highly susceptible to infection and develop pathogen-induced inflammation." (PMID 23189270, 2012). "Increased susceptibility to aspergillosis is also observed in this “at-risk” group in patients carrying a TLR3 +95C/A, but not a TLR3 L412F, SNP." (PMID 23189270, 2012). "The therapeutic efficacy with micafungin in aspergillosis is strictly induced by the activation of the TLR2/dectin-1 and TLR3/TRIF signaling pathways, which regulate the inflammatory/anti-inflammatory balance during infection, mainly by increasing the production of IL-10 and decreased TNF-α." (PMID 33194839, 2020).
autoimmune liver disease (4 papers, 2010 to 2024). "Immunohistochemistry analyses showed that the expression of TLR3 was markedly increased in biliary epithelial cells at sites of ductular reaction in primary biliary cirrhosis and autoimmune hepatitis." (PMID 20936107, 2010). "The critical role of TLR3 in autoimmune hepatitis was clearly demonstrated in a model of hepatitis induced by infection of lymphocytic choriomeningitis virus (LCMV)." (PMID 20936107, 2010). "A recent study indicated that activated liver-specific T cells alone were not sufficient to trigger the liver damage, and TLR3-driven inflammatory cytokine release was required to induce autoimmune liver disease." (PMID 23799121, 2013).
avian influenza (4 papers, 2016 to 2024). Infection of domestic and wild fowl and other birds with influenza A virus. "The binding of TLR3 of duck with the hemagglutinin H5N1 strain of avian influenza is being depicted with certain domains highlighted." (PMID 34970593, 2021). "The binding of TLR3 of duck with the neuraminidase H5N1 strain of avian influenza is being depicted with certain domains highlighted." (PMID 34970593, 2021). "Our findings suggest that therapeutically modulating the TLR3 pathway to reduce lung damage in cases of avian influenza, and possibly other viral pulmonary infections, may be a worthy approach to explore." (PMID 27504984, 2016). "Previous studies have illustrated the upregulation of TLR3 and IFN-β expression in avian tissues after infection with avian influenza, illustrating the significant role of TLR3 in bolstering host defense mechanisms." (PMID 38731436, 2024). "Molecular docking revealed RIGI, TLR3, and TLR7 as the promising genes conferring antiviral immunity against avian influenza." (PMID 34970593, 2021). "Binding for H and N antigens was observed for different strains of avian influenza with RIGI, TLR7, and TLR3." (PMID 34970593, 2021). "The future outcome for the current study is the possible utilization of the identified disease resistant genes (RIGI, TLR3, and TLR7) for the development of avian influenza–resistant chicken with the identified gene insert from duck through gene editing or a transgenic approach." (PMID 34970593, 2021).
chronic fatigue syndrome (4 papers, 2012 to 2025). "Emerging applications, like rintatolimod for chronic fatigue syndrome and post-COVID fatigue, demonstrate the potential of TLR3-targeted strategies." (PMID 39988665, 2025). "Although not yet used in human IBD, the TLR3 agonist rintatolimod has benefits in chronic fatigue syndrome/myalgic encephalomyelitis, a disease of uncertain etiology but with evidence of viral triggers to the disease and impaired natural killer cell function." (PMID 29515999, 2018).
chronic hepatitis C (4 papers, 2013 to 2021). "To seek the role of cellular immune response in chronic hepatitis C patients with antiviral treatment, we investigated the dynamic changes of peripheral Tregs, PD-1 expressing T-cells and TLR3 expressing CD14+ monocytes in the patients." (PMID 24709775, 2014). "It was found that low proportion of baseline TLR3 expressing CD14+ monocytes was a single predictor of cEVR in chronic hepatitis C patients with antiviral treatment [odds ratio (OR) = 2.11, 95% confidence intervals (CI) (1.15–3.88), P = 0.023]." (PMID 24709775, 2014). "In present study, we found that the level of TLR3 expressing CD14+ monocytes was elevated in chronic hepatitis C patients and further increased at 12 weeks, but returned to baseline level at 24 weeks after treatment with IFNα-2b/RBV or PegIFNα-2a/RBV." (PMID 24709775, 2014). "Thus far, TLR3 expression in peripheral blood has not been well analyzed in chronic hepatitis C patients under antiviral treatment." (PMID 24709775, 2014).
contact dermatitis (4 papers, 2018 to 2025). An inflammatory skin condition caused by direct contact between the skin and either an irritating substance or an allergen. "Atopic and contact dermatitis, which are inflammatory skin diseases rooted in hypersensitivity reactions, are closely regulated by TLR3 activation of the inflammatory response." (PMID 39988665, 2025). "TLR3 enhances allergic inflammation in mice by promoting leukocyte infiltration and edema upon skin irritation in contact dermatitis." (PMID 39988665, 2025). "We also reported that TLR3 was expressed in the epidermis of the skin and that in a murine model of contact dermatitis, the severity of skin inflammation was significantly lower in TLR3 KO mice and significantly greater in TLR3Tg mice than in wild-type mice." (PMID 34869401, 2021). "We also reported that TLR3 positively regulates ocular surface‐ and skin inflammation such as contact dermatitis and AD." (PMID 34547828, 2021). "Both irritant contact dermatitis (ICD) (croton oil) as well as ACD (TNCB) were reduced in the absence of TLR3 in knockout (KO) mice and increased in TLR3-overexpressing mice." (PMID 29983912, 2018).
Crohn disease (4 papers, 2018 to 2025). A gastrointestinal disorder characterized by chronic inflammation involving all layers of the intestinal wall, noncaseating granulomas affecting the intestinal wall and regional lymph nodes, and transmural fibrosis. "The potent upregulation of epithelial CCL20, observed in active ulcerative colitis and Crohn’s disease, is primarily induced by TLR3 ligation with dsRNA14." (PMID 40542081, 2025). "For instance, TLR3 is down regulated in intestinal epithelial cells in patients affected by Crohn’s disease." (PMID 30068314, 2018). "Additionally, increased expression of TLR3 and TLR4 was reported in RA patients and TLR4 was upregulated in Crohn’s disease, suggesting GLI3 may regulate the pathology of Crohn’s disease and RA through modulation of IL-6." (PMID 35937499, 2022).
esophageal adenocarcinoma (4 papers, 2021 to 2025). A malignant tumor with glandular differentiation arising predominantly from Barrett mucosa in the lower third of the esophagus. "Here, we analyzed TLR3 mRNA and protein expression in two ESCC lines (TE8 and KYSE180) and one esophageal adenocarcinoma (EAC) line (OE19)." (PMID 40029556, 2025).
fibrosarcoma (4 papers, 2016 to 2025). A malignant mesenchymal fibroblastic neoplasm affecting the soft tissue and bone. "We aimed to analyze the effect of the TLR3 L742F variant in the TLR3-deficient P2.1 fibrosarcoma cell line, which does not produce detectable amounts of TLR3 protein and does not respond to the dsRNA mimic polyinosinic:polycytidylic acid (poly[I:C])." (PMID 32936395, 2020). "Recently it was demonstrated that treatment of fibrosarcomas with anthracyclines, such as doxorubicin, led to a cell-autonomous induction of ISGs via Toll-like receptor 3 but not the cytosolic sensor MDA5." (PMID 27034163, 2016). "In BATF3-deficient mice, bone marrow-derived DCs fail to produce IL-12 upon Toll-like receptor 3 (TLR3) stimulation, and these mice exhibit significantly weakened CD8+T cell responses to West Nile virus and tumor-specific CD8+T cell responses to syngeneic fibrosarcoma." (PMID 39876010, 2025).
fibrosis (4 papers, 2018 to 2022). the formation of excess fibrous connective tissue in an organ or tissue in a reparative or reactive process. "Regarding the initial METAVIR scale scores, liver transaminase levels were lower in patients with advanced fibrosis when correlated with TLR3 and IFNL3 gene expressions." (PMID 34207750, 2021). "For this study, we used a fibrosis model driven by chronic TLR3 activation induced by repetitive administration of the poly(I:C) agonist, the model representative of a viral-induced fibrosis." (PMID 30190498, 2018). "TLR3 signaling is well characterized in murine natural killer (NK) cells, where activation of TLR3 results in a potent anti-fibrotic effect in both 3,5-diethoxycarbonyl-1,4-dihydrocollidine (DDC)-diet- and CCl4-induced murine fibrosis models." (PMID 31717860, 2019).
gastric adenocarcinoma (4 papers, 2019 to 2024). "Some studies suggest that TLR-3 may be a diagnostic marker for gastric adenocarcinoma." (PMID 39273213, 2024).
ischemia (4 papers, 2014 to 2021). A hypoperfusion of the BLOOD through an organ or tissue caused by a PATHOLOGIC CONSTRICTION or obstruction of its BLOOD VESSELS, or an absence of BLOOD CIRCULATION. "Already at 2 h, more TLR3+ signals were noted in the ischemia group compared with controls (p = 0.029)." (PMID 32833183, 2021). "This mobilized adaptation of TLR3 prior to ischemia may activate TRIF and pIRF3 signaling and then increase IFNβ release during subsequent ischemia." (PMID 24914679, 2014). "We hypothesize that signaling via toll-like receptor (TLR)-3, a receptor that is activated upon binding of double-stranded nucleotides, might play a crucial role in the pathogenesis of AKI following ischemia and reperfusion (IR)." (PMID 24736450, 2014).
ischemic stroke (4 papers, 2015 to 2022). A stroke disorder caused by obstruction of blood flow to the brain, due to thrombotic (local blood clot formation) or embolic (due to a blood clot or other material traveling from another site) event. "We conclude that TLR3 modulation by Poly (I:C) could be a potential approach for protection against ischaemic stroke." (PMID 25351293, 2015). "However, the clinical trial of the TLR postconditioning for ischemic stroke is still facing some unsolved issues, such as the choice of the stroke patients and the effective time point for the TLR3 postconditioning." (PMID 25928750, 2015). "Many of the identified genes, including TLR2, TLR3, TLR9, GRN, COL1A1, FN1, and LAMB1, were reported as upregulated genes in previous reports of ischemic stroke." (PMID 35887140, 2022).
leukemia (4 papers, 2020 to 2023). A malignant (clonal) hematologic disorder, involving hematopoietic stem cells and characterized by the presence of primitive or atypical myeloid or lymphoid cells in the bone marrow and the blood. "Functional studies in fibroblasts and human leukemia monocytic THP1 cells showed that both variants individually suppressed TLR3-driven IRF3 transcriptional activity and the type I IFN response in vitro." (PMID 37097753, 2023). "Early induction of Myd88-independent Toll-like receptor 3 signaling results in a significant delay of leukemia development in Pax5+/− mice." (PMID 37620322, 2023).
liver cancer (4 papers, 2017 to 2021). An epithelial or non-epithelial malignant neoplasm that arises from the liver. "The suppression of TLR3 was related to tumor proliferation, angiogenesis, and the inhibition of apoptosis in liver cancer." (PMID 34094905, 2021). "Simultaneously, human liver cancer cell lines Huh7.0 (TLR3 -/-) and Huh7.5.1 (TLR-/- RIG-I -/-) were infected with SFTSV (MOI = 1.0) for 2 hours and cultured for 48hours, expression RNA levels of IFNα and IFNβ were quantified by real-time PCR." (PMID 28234991, 2017). "In particular, it was previously reported that an increase in ACTG1 expression and a decrease in TLR3 expression could be used as biomarkers for the prognosis of liver cancer due to ethanol." (PMID 34066517, 2021).